PREB (prolactin regulatory element binding)
Description:
Guanine nucleotide exchange factor (GEF) that regulates the assembly of the coat protein complex II/COPII in endoplasmic reticulum (ER) to Golgi vesicle-mediated transport. Selectively activates SAR1A and SAR1B by promoting the exchange of guanosine diphosphate (GDP) for guanosine triphosphate (GTP) in these small GTPases. In their activated GTP-bound state, SAR1A and SAR1B insert into the membrane of the endoplasmic reticulum where they recruit the remainder of the coat protein complex II/COPII which is responsible for both the sorting of proteins and the deformation and budding of membranes into vesicles destined to the Golgi. Was first identified based on its probable role in the regulation of pituitary gene transcription. Binds to the prolactin gene (PRL) promoter and seems to activate transcription.
Synonyms: SEC12
Tractability: Antibody: UniProt predicts a signal peptide or a membrane-spanning region. PROTAC: ubiquitination databases record sites on it; its protein half-life has been measured.
Gene: Protein-coding gene on chromosome 2 (27,130,752 to 27,134,671, reverse strand). Ensembl gene ENSG00000138073.
Subcellular location: Endoplasmic reticulum membrane; Nucleus
Subcellular location (Human Protein Atlas): Endoplasmic reticulum
Pathways (Reactome):
Vesicle-mediated transport: COPII-mediated vesicle transport; Cargo concentration in the ER
Cellular responses to stimuli: XBP1(S) activates chaperone genes
Gene Ontology:
Molecular function: guanyl-nucleotide exchange factor activity; protein binding; GTPase binding
Biological process: COPII vesicle coating; endoplasmic reticulum to Golgi vesicle-mediated transport; lipoprotein transport
Cellular component: endoplasmic reticulum exit site; membrane; nucleus; endoplasmic reticulum membrane
Genetic constraint (gnomAD): Loss-of-function variants: 29 observed, 47.61 expected, observed/expected ratio (o/e) 0.61, 90% interval 0.45 to 0.83. The upper end of that interval is the gene's LOEUF score, 0.83, which puts it in group 3 of 6, group 1 being the genes least tolerant of losing a copy. Missense variants: 494 observed, 539.27 expected, observed/expected ratio (o/e) 0.92, 90% interval 0.85 to 0.99. Synonymous variants: 224 observed, 224.05 expected, observed/expected ratio (o/e) 1, 90% interval 0.9 to 1.12.
Homologues: Orthologues: chimpanzee PREB (99% identical), macaque PREB (99% identical), dog PREB (92% identical), pig PREB (92% identical), rabbit PREB (90% identical), rat Preb (89% identical), mouse Preb (88% identical), guinea pig PREB (84% identical), zebrafish preb (57% identical), tropical clawed frog preb (47% identical), Drosophila melanogaster CG9175 (34% identical), Caenorhabditis elegans sec-12 (25% identical).
Diseases named in the same sentence as PREB in open-access papers:
PREB is named in the same sentence as 11 diseases in open-access papers, as found by Europe PMC text mining. Sharing a sentence is not in itself a finding about the gene and the disease. The quoted sentences say what the papers report.
osteosarcoma (2 papers, 2021 to 2022). A usually aggressive malignant bone-forming mesenchymal neoplasm, predominantly affecting adolescents and young adults. "The results revealed that the expression levels STC2 and PREB were elevated clearly in osteosarcoma tissues than in normal tissues, whereas the ATP6V0D1 expression level was significantly downregulated in tumor tissues compared with normal tissues." (PMID 35754801, 2022). "Expression of ABCA3, CTGF, and AMIGO2 were significantly higher in metastatic osteosarcoma samples compared to the primary osteosarcoma samples while the expression of PREB, FHIT, and EXOSC5 were significantly decreased in metastatic osteosarcoma samples." (PMID 34368151, 2021). "Finally, four genes (STC2, PREB, TSPYL2, and ATP6V0D1) were screened to construct and validate a risk signature to predict the prognosis of patients with osteosarcoma." (PMID 35754801, 2022). "Finally, based on the results of previous screening, four UPRRGs (STC2, PREB, TSPYL2, and ATP6V0D1) were identified to establish a risk model for osteosarcoma via the multivariate Cox regression analysis." (PMID 35754801, 2022). "The results of the cell further identified that the expression levels of PREB and STC2 were higher in osteosarcoma cells than in normal osteoblasts, while TSPYL2 and ATP6V0D1 exhibited the opposite results." (PMID 35754801, 2022). "Next, to assess the role of UPRRGs in predicting the prognosis of osteosarcoma, we constructed a prognostic signature to predict the survival of osteosarcoma patients via four genes (STC2, PREB, TSPYL2, and ATP6V0D1)." (PMID 35754801, 2022).
anxiety disorder (1 paper, 2022). A category of psychiatric disorders which are characterized by anxious feelings or fear often accompanied by physical symptoms associated with anxiety. "The authors identified strong associations to individual disorders, such as GHRH with anxiety disorders, PREB with eating disorders, and GRIK5 with bipolar disorder." (PMID 35893041, 2022).
virus infection (1 paper, 2023). "In the subsequent experiments, we confirmed that PFV infection upregulates PREB mRNA expression; moreover, our virus infection experiment results indicated that PFV infection can upregulate endogenous PREB expression." (PMID 37885034, 2023).
PREB also shares sentences with these, for which no sentence is quoted: infection (2 papers); bacterial infection (1); bipolar disorder (1); bladder cancer (1); Chlamydia infection (1); eating disorder (1); pituitary tumor (1); tumor (1).